USP44 (ubiquitin specific peptidase 44)
Diseases named in the same sentence as USP44 in open-access papers (continued):
Sharing a sentence is not in itself a finding about the gene and the disease.
T-cell acute lymphoblastic leukemia (5 papers, 2011 to 2024). Acute lymphoblastic leukemia of T-cell origin. "USP44 deficiency and overexpression are prone to errors in chromosome separation, aneuploidy, and cancer; for example, its overexpression was noted in T-cell acute lymphoblastic leukemia." (PMID 39664521, 2024). "We speculate that the association of USP44 with CD2BP2 may play a role in T-cell ALL." (PMID 39767807, 2024). "USP44 expression analysis in human T-cell acute lymphoblastic leukemia (ALL) has shown overexpression of USP44 compared to healthy donors." (PMID 34572834, 2021). "Lastly, we show that levels of USP44 are highly elevated in human T-cell acute lymphoblastic leukemia, suggesting a role for these molecular defects in the pathogenesis of this disease." (PMID 21853124, 2011). "In contrast, T-cell acute lymphoblastic leukemia (T-ALL) was observed to have higher levels of USP44 mRNA." (PMID 21853124, 2011).
viral infection (5 papers, 2020 to 2025). "Several lines of evidence suggest that USP44 deconjugates K48-linked polyubiquitin from K236 of MITA after viral infection, which in turn inhibits proteasomal degradation of MITA." (PMID 31968013, 2020). "Recently, a portion of cytoplasmic USP44 was reported to migrate to membranes after viral infection to associate with MITA." (PMID 32644293, 2020). "Consistent with our results, USP44-mediated removal of the K48 ubiquitin modification at K236 on STING has been reported to promote STING protein stability following viral infection and enhance antiviral IFN responses." (PMID 37670034, 2023). "Overexpressed stable cell lines were obtained by viral infection of USP44 in 786-O cells and Caki-1 cells." (PMID 32164618, 2020). "Interestingly, a portion of cytoplasmic USP44 migrated to membranes after viral infection." (PMID 31968013, 2020). "In this study, we identified USP44 as a positive regulator of innate immune response to DNA viruses by deubiquitinating and stabilizing MITA after viral infection." (PMID 31968013, 2020). "Given that MITA is a transmembrane protein and that the MITA-USP44 interaction was detected in the membraneous fraction after HSV-1 infection, a simple explanation is that USP44 interacts with MITA and is recruited to membranes following viral infection." (PMID 31968013, 2020).
nasopharyngeal carcinoma (4 papers, 2022 to 2025). A carcinoma arising from the nasopharyngeal epithelium. "Consistently, low USP44 levels were significantly associated with profoundly inferior survival in a large cohort of 376 nasopharyngeal cancer patients all treated by RCT." (PMID 39478631, 2024). "Hypermethylation of the USP44 promoter in nasopharyngeal cancer disrupts this axis, leading to higher Ku80 levels and radioresistance." (PMID 39478631, 2024). "Mechanistically, a recent publication has described radiosensitivity in nasopharyngeal carcinoma mediated by the deubiquitinase USP44 via stabilization of the E3 ubiquitin ligase TRIM25 and subsequent TRIM25-mediated Ku80 degradation." (PMID 39478631, 2024). "In vivo and in vitro studies have both shown that USP44 suppresses tumorigenesis in nasopharyngeal carcinoma by regulating DNA damage repair." (PMID 37204480, 2023).
T-cell leukemia (4 papers, 2011 to 2020). A malignant disease of the T-lymphocytes in the bone marrow, thymus, and/or blood. "USP44 is also over‐expressed by subsets of T cell leukemias where it is thought to induce chromosomal instability." (PMID 32644293, 2020). "Overexpression of USP44 induces chromosomal instability and is frequently observed in human T-cell leukemia." (PMID 30898977, 2019). "Furthermore, we show that USP44 expression is elevated in subset of T-cell leukemias." (PMID 21853124, 2011).
colon cancer (3 papers, 2022 to 2023). "In addition, hypermethylation of the USP44 promoter was found in colon cancer and breast cancer, suggesting that the mechanisms of USP44 in suppressing NPC may be shared by other tumours." (PMID 35079021, 2022).
lung adenocarcinoma (3 papers, 2014 to 2022). A carcinoma that arises from the lung and is characterized by the presence of malignant glandular epithelial cells. "Aneuploidy is very common in human lung adenocarcinoma, and reduced expression of USP44 is frequently observed in patients with lung adenocarcinoma." (PMID 31795161, 2019). "For example, USP44 was downregulated in human lung adenocarcinoma." (PMID 24981056, 2014).
colitis (2 papers, 2020 to 2022). Inflammation of the colon. "In contrast, USP44‐deficient Tregs were less effective at rescuing recipient mice from colitis." (PMID 32644293, 2020). "When considered in concert with our findings from mouse inflammatory disease (colitis) models, these results illustrate the important role played by USP44 in promoting Treg‐mediated immune suppression in vivo." (PMID 32644293, 2020). "In order to determine the importance of USP44 for in vivo Treg function, we utilized a T cell‐induced, mouse model of colitis." (PMID 32644293, 2020).
colorectal adenoma (2 papers, 2020 to 2021). An adenoma that arises from the colon or rectum. "It was also reported that USP44 promoter was methylated in 89% of colorectal adenomas studied (n = 89), while in the matched normal colon mucosa samples only 3% (n = 51) were methylated." (PMID 34572834, 2021). "In colorectal adenomas, USP44 is silenced due to promoter hypermethylation and the mRNA level of USP44 is decreased." (PMID 32285989, 2020). "However, loss of USP44 did not correlate with aneuploidy in colorectal adenomas." (PMID 34572834, 2021).
leukemia (2 papers, 2022 to 2023). A malignant (clonal) hematologic disorder, involving hematopoietic stem cells and characterized by the presence of primitive or atypical myeloid or lymphoid cells in the bone marrow and the blood. "Collectively, in the present study, USP44 contributed to the growth of leukemia cells and suppressed their apoptosis." (PMID 36483601, 2022). "In our study, when USP44 was knockdown, the level of leukemia cells in the bone marrow and spleens was reduced, and the level of leukemia cells infiltrated into the livers and lungs also declined." (PMID 36483601, 2022). "It indicated that USP44 promotes both the growth and infiltration of leukemia cells." (PMID 36483601, 2022).
metastatic prostate carcinoma (2 papers, 2021 to 2024). A carcinoma that arises from the prostate gland and has spread to other anatomic sites. "While these observations appear to contradict our findings, a more recent study reported USP44 promoter methylation in plasma cell-free DNA of metastatic prostate cancer patients, which was significantly associated with worse overall survival." (PMID 39095452, 2024). "Our findings indicate that USP44 promoter is methylated in plasma cell-free DNA of metastatic prostate cancer patients and that detection of USP44 promoter methylation is significantly associated with overall survival (OS) (p = 0.008)." (PMID 34572834, 2021). "We report for the first time that detection of USP44 promoter methylation in plasma cell free DNA provides significant prognostic information in metastatic prostate cancer." (PMID 34572834, 2021). "Kaplan-Meier analysis has shown that in the group of metastatic prostate cancer patients, the detection of USP44 methylation in plasma cfDNA was significantly correlated with worse OS (p = 0.008)." (PMID 34572834, 2021). "In this study we report for the first time that detection of USP44 promoter methylation in plasma cell free DNA provides significant prognostic information in metastatic prostate cancer, since it was significantly correlated with a worse overall survival." (PMID 34572834, 2021).
neuroblastoma (2 papers, 2023 to 2024). Neuroblastoma (NB) is the most common solid, extracranial childhood tumor. "However, USP44, which emerged as a top candidate, is likely to be associated with neuroblastoma development." (PMID 37170124, 2023). "In the context of our recent work, in which we found USP44 to promote the malignant phenotype of the childhood cancer neuroblastoma, we performed this proteomic analysis in the widely used neuroblastoma cell line SH-SY5Y." (PMID 39767807, 2024). "We recently found that USP44 promotes a MYC-like gene expression program in neuroblastoma cells and in murine fibroblasts." (PMID 39767807, 2024). "Reasoning that USP44 promotes the activity of BRCA2, we hypothesized that high levels of BRCA2 may independently associate with outcomes in neuroblastoma." (PMID 39767807, 2024). "Based on the computational analysis, researchers from the Mayo clinic predicts that USP44 showing high expression may play a critical role in neuroblastoma patients." (PMID 37170124, 2023). "We found that HA-tagged USP44 co-precipitated both GFP-tagged and endogenous BRCA2 from SH-SY5Y neuroblastoma cells." (PMID 39767807, 2024). "As we recently found USP44 over-expression to promote aggressive features in neuroblastoma, we used the SH-SY5Y neuroblastoma cell line for this study." (PMID 39767807, 2024). "Recently, we found that USP44 promotes a MYC-like gene expression signature in mouse embryonic fibroblasts and human neuroblastoma cells." (PMID 39767807, 2024). "We next wondered whether the interaction between USP44 and BRCA2 may have implications for survival in patients with neuroblastoma." (PMID 39767807, 2024).
non-small cell lung carcinoma (2 papers, 2021 to 2022). A group of at least three distinct histological types of lung cancer, including non-small cell squamous cell carcinoma, adenocarcinoma, and large cell carcinoma. "In several cancers, including colon, breast, pancreatic, renal, and non-small cell lung cancer, USP44 depicted a low expression." (PMID 36483601, 2022).
prostate tumor (2 papers, 2020 to 2021). "Interestingly, the chr 21q22.2-22.3 genomic region was also identified to be associated with deep deletion events in prostate tumors with high levels of USP44 promoter methylation." (PMID 34572834, 2021). "The comparative analysis of copy number variation data for methHigh and methLow groups (TCGA-PRAD; Firehose Legacy) showed that prostate tumors with higher levels of USP44 promoter methylation are characterized by a higher fraction of genome altered (p < 0.0001)." (PMID 34572834, 2021). "Another recent study found that USP44 deubiquitinates and stabilizes the expression an activity of the histone methyltransferase EZH2 in prostate tumor cells as well as oncogenic mutants of this epigenetic factor with pro‐tumor results." (PMID 32644293, 2020).
(HCMV) infection (1 paper, 2020). "To determine whether USP44 regulates in a cell- and virus-specific manner, we used independent siRNA construct to knockdown USP44 in human foreskin fibroblasts (HFFs), which are permissive to human cytomegalovirus (HCMV) infection." (PMID 31968013, 2020).
acute myeloid leukemia (1 paper, 2022). Acute myeloid leukemia (AML) is a group of neoplasms arising from precursor cells committed to the myeloid cell-line differentiation. "The USP44 gene, harboring the only non-synonymous variant identified in this multi-population GWAS meta-analysis, has been associated with type 2 diabetes, C-reactive protein levels, and acute myeloid leukemia in prior GWAS, but has not been implicated in anthropometric traits in prior studies." (PMID 35653334, 2022).
B-cell lymphoma (1 paper, 2024). "USP44 deficiency in the Emu-Myc mouse B-cell lymphoma model causes early lethality." (PMID 39664521, 2024).
bladder cancer (1 paper, 2025). "The remaining four genes, CRTC1, MB21D2, USP44 and FGFR2, may drive bladder cancer through other mechanisms of pathway crosstalk, which requires further investigation." (PMID 40768543, 2025).
cerebral palsy (1 paper, 2025). A group of disorders affecting the development of movement and posture, often accompanied by disturbances of sensation, perception, cognition, and behavior. "A study indicated methylation of CSRP1 and USP44 genes in patients diagnosed with cerebral palsy born preterm compared with those born preterm without cerebral palsy." (PMID 39906903, 2025).
cholangiocarcinoma (1 paper, 2026). A carcinoma that arises from the intrahepatic biliary tree (intrahepatic cholangiocarcinoma) or from the junction, or adjacent to the junction, of the right and left hepatic ducts (hilar cholangiocarcinoma). "Previous studies have reported that deubiquitinase USP44 participates in the degradation of LIMA1 in cholangiocarcinoma." (PMID 41540000, 2026).
cholesteatoma (1 paper, 2023). A pathologic process characterized by the proliferation of keratinizing squamous epithelium resulting in the accumulation of keratin and cells in the middle ear and/or mastoid. "In this study, we found that USP44 was hypomethylated and downregulated in cholesteatoma compared to that in the control, indicating that USP44 may play an essential role in cholesteatoma development." (PMID 37609036, 2023). "Therefore, we hypothesized that the hypermethylation of USP44 results in its downregulation in cholesteatoma, which may participate in the hyperproliferation of keratinocytes in cholesteatoma." (PMID 37609036, 2023). "However, currently, there are no relevant studies assessing the role of USP44 in the development of cholesteatoma." (PMID 37609036, 2023).
esophageal cancer (1 paper, 2020). A primary or metastatic malignant neoplasm involving the esophagus. "Based on TCGA database and literature search, we analyzed the methylation of KCNA3, USP44, OPLAH and SMTN in esophageal cancer." (PMID 32266120, 2020).
Fanconi anemia (1 paper, 2024). Fanconi anemia (FA) is a hereditary DNA repair disorder characterized by progressive pancytopenia with bone marrow failure, variable congenital malformations and predisposition to develop hematological or solid tumors. "Our results identified a novel association between BRCA2 and USP44, and a previously unknown role for USP44 in the Fanconi anemia DNA repair pathway that may contribute to its role in cancer." (PMID 39767807, 2024). "We validated the association of USP44 with BRCA2, one of the proteins identified in our study—uncovering a previously unknown function of USP44 in the Fanconi anemia DNA repair pathway." (PMID 39767807, 2024). "We found that cells lacking USP44 have a chromosome breakage phenotype similar to that seen in patients with Fanconi anemia." (PMID 39767807, 2024). "We tested the functional role of USP44 in the Fanconi anemia DNA repair pathway through chromosome breakage analysis and found that cells lacking USP44 had a significant increase in chromosome breaks and radial chromosomes." (PMID 39767807, 2024).
Intellectual disability (1 paper, 2023). "Ubiquitin-specific protease 44 (USP44) regulates the spindle assembly checkpoint and has been implicated in intellectual disability, but never BD." (PMID 37402854, 2023).
lentivirus infection (1 paper, 2022). Virus diseases caused by the Lentivirus genus. "Thus USP44 in Jurkat and MOLT-4 cells were knockdown, and USP44 was overexpressed in CCRF-CEM cells through the lentivirus infection system." (PMID 36483601, 2022).
malignant glioma (1 paper, 2017). A grade III or grade IV glioma arising from the central nervous system. "However, the influence of USP44 on ribosome synthesis in human malignant glioma still needs further investigation." (PMID 28938551, 2017).
meningioma (1 paper, 2024). A generally slow growing tumor attached to the dura mater. "We also identified USP44 protein in c-MYC-immunoprecipitated mixtures in both meningioma cell lines." (PMID 37791390, 2024). "More importantly, the role of the CBX7/USP44/c-MYC/LDHA axis is confirmed in human meningioma tissue samples." (PMID 37791390, 2024). "ChIP–qPCR with CBX7 antibody verified the binding of CBX7 at the promoter of USP44 in both meningioma cell lines." (PMID 37791390, 2024). "Altogether, our results shed light on the critical role of CBX7 in meningioma malignancy progression and identify the CBX7/USP44/c-MYC/LDHA axis as a promising therapeutic target against meningioma progression." (PMID 37791390, 2024). "The therapeutical effectiveness of targeting the CBX7/USP44/c-MYC/LDHA axis in meningioma patients needs to be further explored." (PMID 37791390, 2024). "Although the details regarding the specific E3 ubiquitin ligase that targets c-MYC protein for degradation remain to be further elucidated, the present study indicates a novel function of the CBX7/USP44/c-MYC pathway in meningioma." (PMID 37791390, 2024). "Then, HA-tagged USP44 was overexpressed in two CBX7-overexpressing meningioma cell lines." (PMID 37791390, 2024). "The results showed that USP44 overexpression reduced the levels of CBX7-mediated c-MYC ubiquitination in both IOMM-Lee and CH157 meningioma cells." (PMID 37791390, 2024). "First, we only used two representative malignant meningioma cell lines, IOMM-Lee without NF2 mutation and CH157 with NF2 mutation, to explore the regulation and roles of the CBX7/USP44/c-MYC/LDHA axis." (PMID 37791390, 2024). "Mechanistically, CBX7 restoration destabilizes c-MYC protein by transcriptionally suppressing USP44 expression and then inhibits the c-MYC-dependent transactivation of LDHA transcription, thus inhibiting glycolysis activity and subsequent cell proliferation in meningioma cells." (PMID 37791390, 2024). "Although another primary meningioma cell line, HSMN1, was used in the animal model and similar phenotypes were observed, we cannot exclude the existence of other unknown confounders that might affect the conclusion regarding the regulation of the CBX7/USP44/c-MYC/LDHA axis." (PMID 37791390, 2024).
metastatic disease (1 paper, 2021). "Our results indicate on the contrary that loss of USP44 through promoter methylation results in a worse OS in patients with metastatic disease." (PMID 34572834, 2021).
prostate adenocarcinoma (1 paper, 2021). "In the present study we first investigated the molecular profile of prostate adenocarcinomas that are characterized by USP44 promoter methylation through meta-analysis of TCGA data." (PMID 34572834, 2021).
serous ovarian cancer (1 paper, 2021). "In the present study, we examined the methylation status of six gene promoters (BRCA1, CST6, MGMT, RASSF10, SLFN11 and USP44) in high-grade serous ovarian cancer (HGSOC)." (PMID 35008168, 2021).
skin tumors (1 paper, 2021). "There was a significant increase in the rate of skin tumors in Usp44 null mice." (PMID 33937266, 2021). "We found a significant increase in skin tumors in Usp44 null mice compared with wild-type." (PMID 33937266, 2021).
thyroid (1 paper, 2024). "However, promoter hypermethylation-mediated USP44 downregulation promotes thyroid tumorigenesis and progression." (PMID 39430240, 2024).